CXCR4 (C-X-C motif chemokine receptor 4)
Diseases named in the same sentence as CXCR4 in open-access papers (continued):
Sharing a sentence is not in itself a finding about the gene and the disease.
cancer (continued). "To explore the impact of the second-line chemotherapy drug docetaxel on cancer cells and macrophages, we interrogated the mRNA changes induced by CXCR4 on cancer cells." (PMID 34069563, 2021). "High expression of CXCR4 in NSCLC cells have been shown to promote cancer cells-mediated osteoclast differentiation through secreting VCAM1." (PMID 34136487, 2021). "For instance, researchers found that cancer-associated fibroblasts (CAFs) in TME induced epithelial-mesenchymal transition (EMT) and cisplatin resistance in OC via CXCL12/CXCR4 axis." (PMID 33763130, 2021). "Our findings showed that cancer cells that grew post transfection (SDCs) had a significantly lower sphere-forming ability and invasive potential and CXCR4, CD133, and CD105 markers were less expressed compared to pre transfection." (PMID 34012911, 2021). "Beside the cancer, the prognosis of patients with high expression of CXCR4 is also worse than that of patients with low expression of CXCR4." (PMID 34759953, 2021). "The CXCR4/CXCL12 axis is known to play an integral role in promoting cancer cell progression via phosphorylation of Akt at Ser473 (pAktSer473) that induces epithelial-to-mesenchymal transition (EMT)." (PMID 34070538, 2021). "In animal models of metastatic human cancers, T22 confers selectivity for CXCR4-overexpressing cancer stem cells while the bacterial toxin PE24 causes cell death and cancer remission." (PMID 34834337, 2021). "The C-X-C chemokine receptor 4 (CXCR4) is a seven transmembrane G protein-coupled receptor and is involved in various inflammatory and autoimmune diseases, as well as in cancer metastasis and progression." (PMID 34683912, 2021). "Our study reinforces the concept that the plasma levels of SDF-1α indicate the ability to bind circulating cancer cells expressing CXCR4 and, thus, prevent their homing to possible metastatic sites." (PMID 33919589, 2021). "Treatment with CXCR4 antagonists significantly reduces bone marrow colonization of metastatic cancer cells and growth of intraosseous metastasis." (PMID 35177982, 2021). "Correspondingly, CXCR4 antagonism, in combination with current anti-cancer immune checkpoint immunotherapy, targeting PD-1, for example, has recently been the subject of discussion and investigation as a therapeutic approach for clinical application." (PMID 34504486, 2021). "Chemokine CXCL12 has angiogenic properties and greatly contributes to the outgrowth and metastasis of CXCR4-expressiong cancers." (PMID 33962657, 2021). "CXCR4, a chemokine receptor, is out of the common run in regulating various pathological progress, including cancer metastasis, invasion, and migration." (PMID 33522355, 2021). "CXCR4 is an evolutionarily highly conserved G protein-coupled receptor detected in multiple cancers, including lung ADC." (PMID 33637678, 2021). "The suppression of cell migration by ATPγS was attenuated to a similar level as to only siRNA expressed cells, which suggests that CXCR4 is required for the effect of ATPγS on cancer cell migration." (PMID 34503103, 2021). "Overall, our data suggest that CXCR4 expression increases with cancer progression, acquiring clinical significance only in the metastatic setting." (PMID 33507926, 2021). "The upregulation of CXCR4 also aids in the transendothelial migration of cancer cells, which is followed by the invasion of cancer cells to neighboring tissues and organs." (PMID 33467722, 2021). "In that study, the activation of cancer cell migration was suggested to be due to the expression of C-X-C chemokine receptor-type 4 (CXCR-4), which is the target of miR-302a." (PMID 33806538, 2021). "Previous studies have shown that CXCR4 is elevated in MTC tissues and CXCL12/CXCR4 signaling promotes cancer cell proliferation and invasion." (PMID 33962657, 2021). "Here, we identified that CXCR4 acted as an oncogene to promote cancer progression and genetically silencing of CXCR4 increased cisplatin (DDP)-sensitivity in ccRCC in vitro and in vivo." (PMID 34180759, 2021).
cancer (continued). "In cancer, CXCR4-dependent signaling mediates various processes including cell survival, proliferation, migration, adhesion, stress resistance." (PMID 34440844, 2021). "SDF-1 and CXCR4 are commonly highly expressed in various human malignancies, and the SDF-1/CXCR4 axis plays a central role in the development of cancer." (PMID 34531745, 2021). "The activation of CXCL12 and its receptor CXC chemokine receptor 4 (CXCR4) signaling has been shown to promote cancer cell growth and metastasis in various types of cancers." (PMID 34071280, 2021). "Regarding the migration, it has been reported that chemokine/cytokine receptors such as CCR2 and CXCR-4 play key roles in cell migration and metastatic spread in a variety of cancers, including CRC." (PMID 34059044, 2021). "We showed that downregulation of CXCR4 expression was one of the mechanisms for the inhibitory effect of ATP on bone tropic cancer cell migration." (PMID 34503103, 2021). "Upon binding to CXCR4, the MIF/CXCR4 complex is involved in regulation of endothelial progenitor cell migration, metastasis, cancer growth and homing to tumors." (PMID 33273682, 2021). "Despite the great enthusiasm for translation of CXCR4 antagonists into clinically approved cancer therapies, the utilization of these agents in solid tumors has been restricted by poor efficacy and safety concerns." (PMID 33753481, 2021). "Experimentally, plerixafor (a CXCR4 antagonist) has been shown to mobilize disseminated cancer cells from their niches back to the bloodstream." (PMID 34831167, 2021). "According to the literature, ACKR3 has been reported to be co-expressed with CXCR4 to modulate CXCR4 signalling in cancer cells." (PMID 34060588, 2021). "CXCL12/CXCR4/CXCR7 axis plays a role in cancer regulating cell migration and proliferation, as well as angiogenesis." (PMID 33937018, 2021). "Previous studies showed that TFF2 exerts its mitogenic effect through the CXCR4 signaling pathway in pancreatic beta cells and several other cancer cell lines." (PMID 34146542, 2021). "It is revealed that CXCR4/TGF-β1 can mediate the self-differentiation of human BM-MSCs into cancer-related fibroblasts (CAFs) in CRC, thus playing a role in promoting cancer." (PMID 34349805, 2021). "C-X-C motif chemokine receptor 4 (CXCR4), thought to serve a critical role in the regulation of inflammation and cancer biology, has gained a lot of attention in recent years." (PMID 34867329, 2021). "CXCL12 potentiates CXCR7+/CXCR4+ cancer cell trans-endothelial migration toward CCL19 and CXCL13, chemokines expressed by ECs in the lymph nodes." (PMID 33937018, 2021). "Re-expression of CXCR4 following dedifferentiation of the ductal epithelium into stem cell-like phenotype during carcinogenesis promotes cancer cell survival." (PMID 34453639, 2021). "Peroxisome proliferator-activated receptor gamma-dependent downregulation of CXCR4 in cancer cells slows the rate of metastasis." (PMID 33771976, 2021). "CXCR4 is not only involved in cancer metastasis but can also modulate other functions of cancer stem cells." (PMID 34298991, 2021). "In this work, we successfully developed a T140-MB that can be used for US imaging of CXCR4 expression in the vasculature of cancer." (PMID 34793563, 2021). "A biologically significant antimicrobial activity with associated biofilm destruction has been found, for the first time, associated with T22, a short peptide used to selectively target nanomedicines for CXCR4+ human cancers." (PMID 34834337, 2021). "It has been demonstrated that CXCL12 and its receptor CXCR4 are involved in cancer cell proliferation, migration, invasion, and angiogenesis." (PMID 33927188, 2021). "Fully in line with the implication of CXCR4 in B-cell cancers, we found cancer-relevant pathways such as Kras signaling and glycolysis as well as depletion of DNA repair pathways in CXCR4C1013G B cells." (PMID 34363012, 2021).
cancer (continued). "The CXCL12/CXCR-4 axis is one of the most important pathways involved in cancer growth and metastasis." (PMID 34069563, 2021). "CXCL12 and its receptor, CXCR4, are among the most studied chemokine/chemokine receptors in the scenario of cancer metastasis." (PMID 33390169, 2021). "In fact, it has been shown that, in the invasive front of pancreatic tumors, the depletion of a distinct subpopulation of CD133+ and CXCR4+ cancer stem cells significantly reduced the metastatic phenotype without affecting tumorigenesis." (PMID 34793563, 2021). "In more aggressive subtypes, invasive CXCR4+ cancer stem cells have also been identified at distant sites, suggestive of the CXCL12-CXCR4 axis role in invasion and metastasis." (PMID 33546207, 2021). "Here, for the first time, we found that the enhanced survival of cancer cells achieved by TAM was mainly mediated by CXCR4 activation from the increased secretion of CXCL12 from CSF-1 activated TAM." (PMID 34069563, 2021). "Given that CXCR4 acts as an oncogene in ccRCC, and previous data suggested that CXCR4 also regulated drug resistance in cancer treatment, we validated that targeting CXCR4 was effective to improve DDP-sensitivity in ccRCC cells in the present study." (PMID 34180759, 2021). "The CXCR-4 positive cells possess stem cell characteristics and express the cancer stem cell marker, CD133, in tumors of colon and pancreas." (PMID 34885003, 2021). "The data, for the first time, support the notion that downregulation of CXCR4 expression is one of the mechanisms for the inhibitory effect role of ATP in bone tropic cancer cell migration." (PMID 34503103, 2021). "DPPIV plays a significant role in cancer biology and inhibition of DPPIV promotes cancer metastasis via induction of the CXCL12/CXCR4/mTOR/EMT axis, implying a dissemination-suppressive role in cancer." (PMID 34228231, 2021). "Our findings open new perspectives for repurposing RGZ and other thiazolidinedione PPARγ ligands in the treatment of ACC to specifically target the CXCL12/CXCR4 axis in order to counteract cancer progression." (PMID 34834449, 2021). "The discrepancy of preclinical observations and limited clinical success of CXCR4 antagonists as cancer therapy strongly advocates the involvement of some other aspects of CXCR4 biology beyond its classical CXCR4-CXCL12 signaling axis." (PMID 33966046, 2021). "Existing reports suggest that malignant tumors widely express CXCR4, which a paramount factor responsible for rapid growth, metastasis, and vascularization, along with poor prognosis." (PMID 33414415, 2021). "Various inconsistencies in human cancer cell lines with varied levels of CXCR4 expression as well as studies with CXCR4 knock out mice challenged the paradigm of CXCL12 binding to CXCR4." (PMID 34298991, 2021). "Higher levels of CXCR-4 expression have been found in different types of cancer such as cancers of the lung, kidney, liver, colon, oral, esophagus, pancreas and brain." (PMID 34885003, 2021). "The G-protein coupled chemokine receptor, CXCR4, is highly expressed in CRC and has been shown to be associated with cancer stemness, metastasis, and poor prognosis." (PMID 35582377, 2021). "CXCR4 protein expression has long been suggested as a survival prognostic marker in numerous cancers." (PMID 34685420, 2021). "Based on the role of CXCR4 as an oncogenic factor in a variety of cancers, targeting of CXCR4 has been recognized as a highly attractive therapeutic principle since many years." (PMID 33273682, 2021). "It indicates a novel delivery system for CXCR4 siRNA and provides a new strategy for targeting cancer cells by the Nano system." (PMID 34307366, 2021). "The increased expression levels of CXCL12 and CXCR4 detected by immunohistochemistry in cancer tissues were 50%–78% and 61%–80%, respectively, showing significantly higher levels than found in the corresponding normal tissues." (PMID 33710803, 2021).
cancer (continued). "SDF-1/CXCR-4 signaling regulates proliferation, angiogenesis, chemotaxis and metastasis of cancer cells." (PMID 34885003, 2021). "AMD3100 inhibits CXCR4 activity and blocks the CXCL12/CXCR4 axis, thereby inhibiting the contribution of both stromal and cancer cells to liver metastasis." (PMID 34555268, 2021). "Altogether, our data establish that CXCR4 inversely alters the expression of DR5, and loss of its function results in TRAIL-mediated sensitization of cancer cells." (PMID 33966046, 2021). "Numerous studies have shown that both CXCL12 and its receptor CXCR4 are up-regulated in various cancers." (PMID 33962657, 2021). "CXCR4 (CD184) is a seven-transmembrane G-protein-coupled chemokine receptor known for its ability to mediate the metastasis of a variety of cancers." (PMID 34638956, 2021). "Recent studies have suggested that CXCR7, like CXCR4, is important for cancer cell survival, migration, adhesion, angiogenesis, and metastasis." (PMID 34298991, 2021). "In the same study, we also showed the regulation of cancer-metastasis-related proteins, such as e-cadherin, tetraspanin 8 (Tspan 8), and C-X-C motif chemokine receptor 4 (CXCR4), exerted by SB water extract." (PMID 33918834, 2021). "Many studies have shown that CXCR4 is one of the markers for cancer stem cells in various types of cancer." (PMID 33414415, 2021). "Consistent with the previous studies, CXCR4 had been widely reported as an unfavorable prognostic indicator of various cancers, including GC." (PMID 34113647, 2021). "CD133+/CXCR-4+ cancer stem cells were found to play a pivotal role in metastasis of colorectal cancer and the EMT makes them more migratory." (PMID 34885003, 2021). "C-X-C chemokine receptor type 4 (CXCR4) has been demonstrated to be overexpressed in numerous types of cancer." (PMID 34220311, 2021). "Multiple antagonists of CXCR4 including bicyclams (AMD3100) and T22, as well as peptide analogues designed for the N-terminal region of CXCL12, such as TN14003, CTCE-9908, and ALX40-4C are currently used to target CXCR4 in various cancers." (PMID 34298991, 2021). "High CXCL12/SDF-1 level is seen in metastatic lymph nodes and CXCR4 upregulation in cancer cell lines exposed to pDC conditioned media." (PMID 34337083, 2021). "CXCR4 was shown to be essential for various fundamental aspects of cancer, such as primary tumor growth, cancer cell migration, and the establishment of metastatic sites." (PMID 34684878, 2021). "CXCR4 is selectively induced by activating HIF-1 on different types of cancer cells under hypoxic conditions." (PMID 33771976, 2021). "The importance of the CXCL12/CXCR4 axis in cancer has been extensively shown, which translates in a number of approaches to target this axis." (PMID 34503058, 2021). "CXCR4 is a member of the C-X-C chemokine receptor family and is involved in the regulation of many types of cancer." (PMID 35002537, 2021). "In this work, we developed a targeted microbubble (MB) for imaging of vascular CXCR4 expression in cancer." (PMID 34793563, 2021). "Since the CXCL12-CXCR4 axis is essential for cancer metastasis, many CXCR4 antagonists are in clinical use/development for cancer therapy." (PMID 33390169, 2021). "CXCL12‐CXCR4 is the most commonly overexpressed signaling pathway in a variety of cancers and a number of small‐molecule drugs and peptide inhibitors that target CXCR4 have been developed." (PMID 33463063, 2021). "Taken together, we concluded that CXCR4 ablation hindered cancer progression and enhanced DDP-sensitivity in ccRCC, and the present study identified a novel therapeutic biomarker for ccRCC." (PMID 34180759, 2021). "Inhibiting CXCR4, a CXCL12 receptor, induced T cell accumulation among cancer cells and synergized with anti-PD-L1 to cause cancer regression." (PMID 34290984, 2021). "CXCL12 is the main ligand of chemokine receptor 4 (CXCR4) and overexpressed in metastasis of various cancers including CRC." (PMID 34288395, 2021).
cancer (continued). "The CXCR-4+/CD133+ cancer cell population was increased during EMT and possesses the characteristics of stem cells." (PMID 34885003, 2021). "Reduction of CTNND1 promotes bone metastasis of TNBC cells by facilitating homing cancer cells to bone and the survival of the metastatic cells via upregulating CXCR4/CXCL12 axis and neutrophils Infiltration in bone." (PMID 34830862, 2021). "Chemokine receptor 4 (CXCR4) is highly expressed in various types of cancer, and is considered important for mobilization, migration, proliferation and survival of different cell types." (PMID 33953222, 2021). "Further, intracellular CXCR4 protein contributes significantly to the tumorigenic potential of cancer cells, and future therapies should majorly focus on targeting CXCR4 protein and not only CXCR4 mediated signals." (PMID 33966046, 2021). "Previous studies have demonstrated that CXCR4 accelerates the metastasis, invasion, growth, and therapeutic resistance of cancer." (PMID 34568309, 2021). "We also explore unique signaling, TME and stromal targeting via novel small molecule inhibitors, which target KRAS, FAK, CCR2/CCR5, CXCR4, PARP and cancer-associated fibroblasts." (PMID 34771675, 2021). "In line with this assumption, many pre-clinical studies report on promising anti-cancer effects of anti-CXCR4 antibodies when applied to target involved immune and cancer cells." (PMID 34504486, 2021). "CXCR4 has been recognized as a key regulatory mechanism for cancer growth and invasion for a long time and has emerged as a promising target for anti-cancer drugs." (PMID 33669329, 2021). "The tracer was shown to have overall good kinetics and the potential to be exploited in clinical studies for the detection of CXCR4 expression in human cancers." (PMID 34500609, 2021). "Interaction between CXCL12 and CXCR4 also facilitates the adhesion of cancer cells to microvascular endothelial cells via an integrin β1-based mechanism, which eventually results in an elevated rate of melanoma pulmonary metastases." (PMID 33430277, 2021). "CXCL12/CXCR4 is a well-studied chemokine ligand–receptor pair, which plays an important role in homeostasis and pathogenesis in malignant diseases including cancer." (PMID 34060588, 2021). "Promising results from PET studies using [68Ga]pentixafor, [64Cu]DOTA-ECL1i, and [64Cu]DOTA-DAPTA-comb expanded the boundaries of cancer and cardiac disorder imaging for CXCR4, CCR2, and CCR5, respectively." (PMID 34500609, 2021). "The use of anti-VEGF antibodies in CRC upregulated CXCL12/CXCR4 signaling between cancer cells and Ly6low monocytes, increasing the latter population and thus generating an immunosuppressive environment and increasing the possibility of therapeutic failure." (PMID 33530455, 2021). "Patients with high CXCR4 overexpression (≥6-fold) in TNBC had a significantly higher incidence of cancer recurrence and cancer-related death than the low CXCR4 group (<6-fold)." (PMID 34198652, 2021). "Recent advances in CXCR4 antagonist development seek to exploit its potential anti-cancer effects in combination with immune checkpoint inhibitor therapy." (PMID 34504486, 2021). "About 50% of these cancer hybrid cells also expressed the promigratory chemokine receptor CXCR4, suggesting an acquired metastatic capacity." (PMID 34503305, 2021). "According to the previous publications, CXCR4 positively regulates the malignant phenotypes to facilitate cancer progression, which were validated by our results in this study." (PMID 34180759, 2021). "CXCR4 expression in cancer cells is negatively related to the prognosis of the disease and serves as an independent factor of other prognostic parameters." (PMID 34322132, 2021). "In MRE11-overexpressing cells, RNA expression of CXCR4, a cell membrane protein involved in cancer cell migration and invasion, was increased, but this was reversed when cells were cotreated with siCXCR4." (PMID 33927349, 2021).